MREG (melanoregulin)
Description:
Probably functions as a cargo-recognition protein that couples cytoplasmic vesicles to the transport machinery. Plays a role in hair pigmentation, a process that involves shedding of melanosome-containing vesicles from melanocytes, followed by phagocytosis of the melanosome-containing vesicles by keratinocytes. Functions on melanosomes as receptor for RILP and the complex formed by RILP and DCTN1, and thereby contributes to retrograde melanosome transport from the cell periphery to the center. Overexpression causes accumulation of late endosomes and/or lysosomes at the microtubule organising center (MTOC) at the center of the cell. Probably binds cholesterol and requires the presence of cholesterol in membranes to function in microtubule-mediated retrograde organelle transport. Binds phosphatidylinositol 3-phosphate, phosphatidylinositol 4-phosphate, phosphatidylinositol 5-phosphate and phosphatidylinositol 3,5-bisphosphate, but not phosphatidylinositol 3,4-bisphosphate or phosphatidylinositol 4,5-bisphosphate (By similarity). Required for normal phagosome clearing and normal activation of lysosomal enzymes in lysosomes from retinal pigment epithelium cells. Required for normal degradation of the lipofuscin component N-retinylidene-N-retinylethanolamine (A2E) in the eye. May function in membrane fusion and regulate the biogenesis of disk membranes of photoreceptor rod cells (By similarity).
Synonyms: DSU; FLJ10116; WDT2
Tractability: Antibody: UniProt places it where antibodies can reach, with medium confidence; its Gene Ontology location is reachable by antibodies, with medium confidence. PROTAC: ubiquitination databases record sites on it.
Gene: Protein-coding gene on chromosome 2 (215,942,584 to 216,034,096, reverse strand). Ensembl gene ENSG00000118242.
Subcellular location: Apical cell membrane; Melanosome membrane; Lysosome membrane; Cytoplasmic vesicle membrane
Subcellular location (Human Protein Atlas): Vesicles
Gene Ontology:
Molecular function: protein binding; phosphatidylinositol binding
Biological process: melanocyte differentiation; melanosome localization; melanosome transport; phagosome maturation; minus-end-directed organelle transport along microtubule
Cellular component: apical plasma membrane; cytoplasmic vesicle membrane; late endosome membrane; lysosomal membrane; melanosome; melanosome membrane; organelle membrane; protein-containing complex
Genetic constraint (gnomAD): Loss-of-function variants: 18 observed, 16.6 expected, observed/expected ratio (o/e) 1.08, 90% interval 0.75 to 1.6. The upper end of that interval is the gene's LOEUF score, 1.6, which puts it in group 6 of 6, group 1 being the genes least tolerant of losing a copy. Missense variants: 210 observed, 200.13 expected, observed/expected ratio (o/e) 1.05, 90% interval 0.94 to 1.18. Synonymous variants: 77 observed, 73.52 expected, observed/expected ratio (o/e) 1.05, 90% interval 0.87 to 1.27.
Homologues: Orthologues: chimpanzee MREG (99% identical), dog MREG (90% identical), rabbit MREG (89% identical), guinea pig MREG (87% identical), mouse Mreg (86% identical), rat Mreg (85% identical), pig MREG (84% identical).
Diseases named in the same sentence as MREG in open-access papers:
MREG is named in the same sentence as 10 diseases in open-access papers, as found by Europe PMC text mining. Sharing a sentence is not in itself a finding about the gene and the disease. The quoted sentences say what the papers report.
thyroid cancer (3 papers, 2019 to 2024). "Only MREG was found to be down-regulated in expression in thyroid cancer tissues, and knockdown of MREG promoted cancer cell proliferation and invasion." (PMID 38517922, 2024). "MREG is reported to suppress thyroid cancer cell invasion and proliferation through PI3K/Akt-mTOR signaling pathway." (PMID 34178023, 2021). "Furthermore, melanoregulin has been shown to regulate the invasion and proliferation of thyroid cancer cells via PI3K/AKT/mTOR pathway." (PMID 31223424, 2019).
albinism (1 paper, 2012). A congenital disorder characterized by partial or complete absence of melanin pigment in the eyes, hair, or skin. "While other forms of albinism affect both skin (hair follicles) and retinal pigment, the effects of MREG and OA1 appear to be primarily restricted to the eyes." (PMID 22984402, 2012).
periodontal disease (1 paper, 2017). "In addition, co-localization of LC3 and melanoregulin (MREG) was found in gingival epithelial cells isolated from severe periodontal disease-affected individuals, while this effect was absent in cells from healthy or moderately affected individuals." (PMID 28690552, 2017).
periodontitis (1 paper, 2022). An acute or chronic inflammatory process that affects the tissues that surround and support the teeth. "The result showed that the expression of LC3, Beclin-1, and MREG in periodontitis was less than that in healthy people." (PMID 35846745, 2022). "It is speculated that P. gingivalis may affect the expression of MREG and LC3, and inhibit the normal autophagic process in HGECs of periodontitis patients." (PMID 35846745, 2022).
cancer (4 papers, 2013 to 2024). A tumor composed of atypical neoplastic, often pleomorphic cells that invade other tissues. "Similarly, melanoregulin (MREG) downregulates the phosphatidylinositol 3 kinase (PI3K)/Akt-mTOR signaling pathway and simultaneously inhibits the invasion and proliferation of cancer cells." (PMID 36761693, 2022).
MREG also shares sentences with these, for which no sentence is quoted: breast carcinoma (2 papers); cerebral malaria (1); liver cancer (1); ovarian carcinoma (1); tumor (1).